IRS1 (insulin receptor substrate 1)
Diseases named in the same sentence as IRS1 in open-access papers (continued):
Sharing a sentence is not in itself a finding about the gene and the disease.
Insulin resistance (continued). "Hepatic steatosis or hepatic fat infiltration may induce hepatic insulin resistance through activation of JNK1 and PKC-epsilon, which may interfere with tyrosine phosphorylation of IRS-1 and IRS-2." (PMID 35968500, 2022). "Tau knock-out mice have impaired IRS-1 tyrosine phosphorylation (required to activate insulin signaling) and increased Ser636 IRS-1 phosphorylation (which inhibits insulin signaling) leading to insulin resistance." (PMID 35281504, 2022). "TNF-α plays a critical role in developing insulin resistance by reducing the insulin-regulated glucose transporter type 4 (GLUT4) expression, located in adipocytes, skeletal, and cardiac muscles, and through the induction of serine phosphorylation of IRS1." (PMID 35682958, 2022). "In adult SL offspring, muscular hypermethylation of insulin receptor substrate 1 (IRS1) promotes lower IRS1 expression, which could contribute to insulin resistance." (PMID 35631188, 2022). "Although literature is scarce, the reduction of GLUT-4, GLUT-3 and IRS-1 expression in GDM patients could be correlated with a lower SHBG activity, which could favor insulin resistance." (PMID 35450164, 2022). "A clinical study showed that CTRP1 could inhibit the phosphorylation of IRS-1, a well-known upstream protein of AKT, to improve insulin resistance." (PMID 36195912, 2022). "The mechanisms at which these ameliorating effects are achieved may be via GLUT-4, IRS-1, PI3K and AKT gene upregulation which may probably enhance GLUT-4 translocation, reduce insulin resistance and induce PI3K/AKT signalling pathway." (PMID 35739183, 2022). "A study on animal models has shown that the protective effect of DHEA on high-fat-induced hepatic glycolipid metabolic disorder and insulin resistance might be achieved through the activation of the AMPK-PGC-1α-NRF-1 and IRS1-AKT-GLUT2 signaling pathways." (PMID 35741728, 2022). "Progesterone could induce insulin resistance by inhibiting GLUT-4 translocation, decreasing the expression of insulin receptor substrate-1 (IRS-1), and blocking the glucose absorption by adipocytes." (PMID 36407549, 2022). "The objective of this study was to determine the potential role of TSH in the suppression of insulin receptor substrate-1 (IRS-1) expression and IRS-1 tyrosyl phosphorylation, which might contribute to insulin resistance." (PMID 35320949, 2022). "In normal pregnancies, placental hormones, e.g., PL, progesterone, cortisol, GH and prolactin, can decrease the phosphorylation of insulin receptor substrate 1 (IRS-1), a key regulator of this signaling pathway, decreasing insulin sensitivity and β-cell function, leading to insulin resistance." (PMID 35813659, 2022). "The expression levels of IRS-1 and GLUT4 are indicative of the state of insulin resistance." (PMID 34699329, 2021). "Chronic mTORC1 activation increases insulin resistance by regulating negative feedback through the phosphorylation of IRS-1." (PMID 33546399, 2021). "Since novel antibodies against JNK-dependent S307 phosphorylation of IRS1 did not work properly for Western blotting, we tested S1101 phosphorylation as a marker of insulin resistance." (PMID 33946318, 2021). "Similarly, in obese insulin-resistant rats, GRE administration upregulated relevant genes involved in the insulin signaling pathway and glucose metabolism, namely Insr, Irs1, Irs2, Pi3k and Ampk." (PMID 34208379, 2021). "We hypothesize that the abnormal phosphorylation of IRS1 occurring in patients with T2DM and/or insulin-resistance may somehow interfere with the TSHR signaling pathway, thus inducing an increase of serum TSH levels." (PMID 33058005, 2021). "IRS1 and IRS2 are important for the development of NAFLD in the presence of insulin resistance." (PMID 34449768, 2021). "One mechanism mediating insulin resistance involves phosphorylation of serine residues in IRS-1, inducing its conformational change that in turn can lead to disruption of the interaction between IR and IRS-1." (PMID 34069933, 2021).
Insulin resistance (continued). "Likewise, it has been reported that T2DM patients carrying the IRS1 variant rs2943641 CC genotype might obtain more benefits in weight loss and improvement of insulin resistance than those without this genotype when they adhere to a high-carbohydrate and low-fat diet." (PMID 33503923, 2021). "TNFα may also play a critical role in insulin resistance, specifically by downregulation of GLUT-4 and IRS-1." (PMID 34949179, 2021). "Also, adipose tissue insulin resistance, evidenced by increased PTP1B and insulin receptor substrate 1 (IRS1) inhibitory phosphorylation and decreased Akt activity, was detected." (PMID 34869524, 2021). "CCL4 antibody-treated mice had decreased levels of phosphorylated IRS-1 in both skeletal muscle and liver tissues compared to those in the untreated db/db mice, implying the beneficial effects of CCL4 inhibition on improving insulin resistance." (PMID 33968046, 2021). "Persistent JNK activation may be largely responsible for the neuronal insulin resistance typical of AD, as JNK can confer an inhibitory phosphorylation on insulin receptor substrate-1 (IRS-1), a mediator of the insulin signaling pathway." (PMID 33669995, 2021). "In addition, Ex-4 improved the basal expression of IRS-1 and GSK-3β phosphorylation in neurons under PA-induced insulin resistance, compared to the control group." (PMID 33435277, 2021). "In addition, in adipose tissue, miR-155 promotes insulin resistance by downregulation of GLUT-4, decreasing the tyrosine phosphorylation of the insulin receptor and of IRS1, as well as attenuating the activation of Akt/PKB." (PMID 34440850, 2021). "More importantly, cardiac insulin resistance is a feature of human HF, and IRS1, but not IRS2, was found to be downregulated in failing human hearts." (PMID 32223896, 2020). "Cytokines induce hepatic and peripheral insulin resistance in part via SOCS, which antagonize the insulin receptor mediated phosphorylation of IRS1/2 and can increase hepatic fat accumulation via antagonizing STAT3-mediated inhibition of the lipogenic transcription factor SREBP-1c." (PMID 32183037, 2020). "Simultaneous deletion of IRS1 and IRS2 genes in the liver of mice could inhibit the phosphorylation cascade of AKT, leading to hyperglycemia, hyperinsulinemia, and insulin resistance." (PMID 32280711, 2020). "Signaling of insulin occurs via insulin receptor substrate 2 (IRS2) and is not suppressed during insulin resistance, while signaling via IRS1 for counterregulatory mechanisms, including local NO production, is impaired." (PMID 32819363, 2020). "Aβ, in turn, induces insulin resistance and GSK-3β by trapping insulin receptors in the neuronal cytoplasm and promoting inhibitory serine phosphorylation of insulin pathway components, for example IRS-1." (PMID 33381011, 2020). "Therefore, we tested if the gWAT-derived exosomal miR-222 induces insulin resistance in the liver and skeletal muscle tissues of HFD-fed obese model mice by repressing IRS1." (PMID 33197889, 2020). "PTH also induced an increase of insulin receptor substrate-1 (IRS-1) phosphorylation on serine 307, which has been reported to down-regulate insulin intracellular signaling, resulting in an increase in peripheral insulin resistance." (PMID 33207657, 2020). "Thus, gWAT-derived serum exosomal miR-222 appears to promote insulin resistance in the liver and skeletal muscle of HFD-fed obese mice by suppressing IRS1 expression." (PMID 33197889, 2020). "However, insulin resistance in women with PCOS has been attributed to increased insulin receptor and insulin receptor substrate 1 (IRS1) serine phosphorylation in muscle, with impaired insulin signaling that affects the metabolic but not the mitogenic pathway." (PMID 33467251, 2020).
Insulin resistance (continued). "In our analysis, phosphatase binding and protein serine/threonine kinase activity involving Akt phosphorylation and IRS-1 and PI3K expression were core targets in signal transduction, metabolism regulation, cell proliferation, inflammation, and insulin resistance in DN." (PMID 32190104, 2020). "Most prominently, female offspring from 1000 mGy dams showed increased expression of genes which contribute to insulin resistance and gluconeogenesis (PPARG1a/b, SOCS3 and PEPCK) at 4 months of age, while genes involved in glucose metabolism were unaffected (GSK, IRS1, GLUT2)." (PMID 32315370, 2020). "Therefore, defects at the proximal level of insulin signaling that involve INSR, IRS1, PI3K, and Akt pathways are more evident in skeletal muscle insulin resistance, resulting in a decrease in insulin‐stimulated glucose uptake." (PMID 33038072, 2020). "It was reported that mice that underwent IUGR followed by catch-up growth display peripheral and central insulin resistance in adulthood, and that expressions and/or phosphorylation of PI3K p110 subunit and phospho-IRS1 were altered in the arcuate nucleus of the hypothalamus." (PMID 31071176, 2019). "In the case of IRS1 (cg21511036), AKT1S1 (cg03813033), ADCY2 (cg12566890 and EHMT2 (cg00210002) are hypomethylated, whereas AKT1 (cg01749142), FOXO3 (15283498), are hypermethylated in subjects with insulin resistance and hypertriglyceridemia." (PMID 30926763, 2019). "Decreased IRS-1 serine phosphorylation is associated with negative effects on the insulin signaling pathway and has been described in connection with TNF-α-induced insulin resistance." (PMID 30863203, 2019). "Hyperinsulinemia that observed in T2DM and T2DM_CAD groups, may down regulate IRS1 and IRS2 via p38-MAPK and triggers insulin resistance in liver and skeletal muscle." (PMID 30674322, 2019). "Based on our observation that NGF mainly ameliorates insulin resistance by IRS1 activation, we thus asked whether the effect of NGF on glucose metabolism is mediated by IRS1 in cholinergic neurons." (PMID 29736736, 2019). "They indicated that progesterone could induce insulin resistance by the inhibition of GLUT-4 translocation, a decrease in the expression of the insulin receptor substrate-1 (IRS-1), and the uptake of glucose by adipocytes." (PMID 31656196, 2019). "In addition, the insulin signaling pathway (IRS-1/AKT/FOXO1) was activated, further demonstrating that Nifu mitigates PA-induced insulin resistance by activating insulin signaling." (PMID 35540668, 2019). "It is worth mentioning that BDNF administration exerted anorectic effects on HFD-fed mice but without significantly interfering with peripheral insulin resistance nor counteracting IRS1 inhibition in the ovaries." (PMID 31641124, 2019). "Consistently, calculation of HOMA-IR (ESM), HOMA-B (ESM), QUICKI (ESM) and measurement of phosphorylated IRS-1 in liver lysates, showed that animals treated with STZ, either alone or in combination with CFTRinh172, displayed evidence of insulin resistance and poor insulin sensitivity." (PMID 31375720, 2019). "The IRS‐1 expression, previously decreased upon feeding HFD, increased with Cr complex supplementations, particularly CrHis, indicating the effects of Cr in improving insulin resistance by enhancing insulin signaling." (PMID 30680172, 2019). "After 3 weeks of chronic corticosterone treatment, further changes were found in Irs1, P85α, and P110β mRNA in skeletal muscle, WAT, and BAT in a manner associated with insulin resistance (data not shown)." (PMID 30794724, 2019). "Dysfunction of IRS-1 and IRS-2 would lead to insulin resistance and NAFLD." (PMID 31805951, 2019). "The mRNA expression levels of IRS-1 and GLUT4 were compared as markers of insulin resistance." (PMID 30445954, 2018).
Insulin resistance (continued). "Because mice with homozygous disruption of IRS1 display mild phenotypes such as growth retardation and mild insulin resistance, but not diabetes 78, 79, little is known about the function of IRS1 in the brain." (PMID 29988567, 2018). "Hepatic IRS-1 and IRS-2 play a pivotal role in mediating insulin-dependent regulation of glucose and lipid metabolism; dysregulation of abundance and/or phosphorylation status of IRS-1 and IRS-2 in the liver are significant factors in the pathogenesis of insulin resistance and type 2 diabetes." (PMID 30225267, 2018). "Therefore, we evaluated the expressions of INSR, IRS1, PI3K, Akt, and GLUT4, the major proteins closely related to insulin resistance in the skeletal muscle." (PMID 29686718, 2018). "Finally, SAMC can reduce inflammation through NF-κB and improve lipid homeostasis and insulin resistance through the AMPK and IRS-1/PI3K/Akt pathway." (PMID 30201879, 2018). "Prolonged activation of mTORC1 induces insulin resistance in adipose tissue through the S6K1-mediated inhibition of insulin signaling that disrupts the recruitment and activation of PI3K via phosphorylation of insulin receptor substrate-1 (IRS-1)." (PMID 30305865, 2018). "Moreover, GEE activates IRS-1 and inhibits activation of MAPK pathways, and therefore should ameliorate insulin resistance and the clinical signs of diabetes." (PMID 29316644, 2018). "However, RES treatment alleviated insulin resistance, increased the expressions of pAkt, GLUT4 and IRS-1 in WAT, and decreased serum proinflammatory cytokine levels, macrophage infiltration and CCR2 expression in WAT." (PMID 29967759, 2018). "Factors that interfere with either expression or phosphorylation of IRS1 and IRS2 may contribute to insulin resistance." (PMID 30602666, 2018). "NAFLD or liver fatty infiltration may induce hepatic insulin resistance by activating PKC-epsilon and JNK1, which may interfere with the tyrosine phosphorylation of IRS-1 and IRS-2." (PMID 29051770, 2017). "IRS-1 mS307 (hS312) has been shown to protect mice against HFD-induced insulin resistance without affecting phosphorylation at other serine residues and while maintaining PI3K binding to IRS-1." (PMID 29077002, 2017). "Along with the decrease in the phosphorylation of insulin receptor substrates (IRS-1 and IRS-2) and in PI3-K activity observed in insulin resistance, the translocation of glucose transporters and the activity of key enzymes implicated in glucose homeostasis are also reduced." (PMID 28259166, 2017). "Ser-307 phosphorylation of IRS-1 is considered an important negative indicator of insulin resistance, followed by reduced PI3K/Akt phosphorylation." (PMID 29096724, 2017). "In type 2 diabetic patients, increased insulin resistance and resulting hyperinsulinemia might upregulate the production of insulin-like growth factor-1 (IGF-1) and insulin receptor subtrate-1 (IRS-1)." (PMID 28333991, 2017). "In contrast, knockin mice having IRS1 with alanine replacingSer312 develop severe insulin resistance, which strongly refutes phosphorylation of IRS1 atSer312 mediating a negative feedback." (PMID 27986865, 2017). "Several studies showed that CPAE can improve insulin resistance by inhibiting serine phosphorylation of IRS-1, thereby restoring tyrosine phosphorylation of IRS-1 and increasing Akt phosphorylation in the muscle tissue of mice with adipose dysfunction and insulin resistance." (PMID 28684967, 2017). "Further analysis of the data and discussion of the implication of miR-96 in insulin resistance and the pathogenesis of type 2 diabetes are presented in "Induction of miR-96 by dietary saturated fatty acids exacerbates hepatic insulin resistance through the suppression of INSR and IRS-1"." (PMID 29124099, 2017).
Insulin resistance (continued). "The increase of phosphorylation in IRS-1 and PI3K serine, as happens in insulin-resistance, is mediated by the c-Jun N-terminal kinase (JNK) and nuclear factor-κB kinase β (IKK-β) activation, as happens in experimental models of insulin-resistance induced by HFD or palmitic acid." (PMID 28125040, 2017). "We demonstrate that hepatic Irs2-knockout mice develop ‘selective insulin resistance', whereas mice lacking in Irs1, or both Irs1 and Irs2, develop ‘total insulin resistance'." (PMID 27708333, 2016). "Mice lacking IRS-1 developed insulin resistance with hyperinsulinemia, not diabetes, but displayed features of metabolic syndrome (hypertension and hypertriglyceridaemia)." (PMID 27413253, 2016). "Animals without IRS-2 exhibited insulin resistance with fasting hyperglycemia, due to inadequate insulin production, which in final resulted in diabetes, which was worse than lack of IRS-1." (PMID 27413253, 2016). "Mice lacking in hepatic Irs2 develop ‘selective insulin resistance', whereas mice lacking in hepatic Irs1, or both hepatic Irs1 and Irs2 develop ‘total insulin resistance'." (PMID 27708333, 2016). "The difference between the role of IRS1 and IRS2 in insulin signaling cascade could account for the existence of selective insulin resistance in liver." (PMID 27247938, 2016). "IRS-1 is an important factor in the insulin signaling pathway, and TNF-α diminishes insulin-induced tyrosine phosphorylation of IRS-1 during the process of insulin resistance." (PMID 27324794, 2016). "The dual knockdown of IRS-1 and IRS-2 resulted in systemic insulin resistance and hepatosteatosis." (PMID 26866272, 2016). "It has been shown that activation of the IKK-β and JNK pathways increases IRS-1 serine phosphorylation which leads to suppression of insulin signaling and that suppression of the IKK pathway decreases insulin resistance and ameliorates glucose intolerance in diabetic mice." (PMID 27034691, 2016). "In vascular endothelial cells, IR/IRS1/PI3K/Akt pathways are thought to be attenuated in insulin resistance, while the ERK/MAPK pathways are not affected in obese Zucker rats, suggesting the existence of selective insulin resistance." (PMID 27247938, 2016). "In addition, previous studies have reported that phosphorylation of IRS-1 at serine 307, a JNK phosphorylation site, is increased in obesity-induced insulin resistance." (PMID 26172834, 2015). "The development of insulin resistance in the 1-day unloaded soleus is not due to impaired functionality of elements involved in the IR/IRS-1/PI3-kinase/Akt signaling pathway." (PMID 25713812, 2015). "Thus, while there is converging evidence for IRS1 as the causal locus, it is currently not clear whether insulin signaling in skeletal muscle or adipose tissue biology that may result in insulin resistance is primarily affected by the genomic region upstream of IRS1." (PMID 26090471, 2015). "Moreover, it has been shown that TLR2 is central to palmitate-induced insulin resistance, via JNK-mediated phosphorylation of IRS1/2." (PMID 25814786, 2015). "The multiple physiological consequences of IRS-1 phosphorylations are seen in increased activation of the mTOR pathway along with enhanced phosphorylation of IRS-1 at Ser307 and Ser636/639 that occur in animal models of insulin resistance." (PMID 26474286, 2015). "Reduction in insulin stimulated phosphorylation of the insulin receptor and IRS-1, and reduced activity of PI3-kinase in T2DM suggest that defective insulin signalling may be, at least in part, responsible for insulin resistance." (PMID 25876175, 2015). "Many studies have suggested that serine phosphorylation of IRS-1 is elevated in conditions of insulin resistance, and provides negative feedback to insulin signaling to attenuate insulin-stimulated tyrosine phosphorylation." (PMID 25912041, 2015).